VIM (vimentin)
Diseases named in the same sentence as VIM in open-access papers (continued):
Sharing a sentence is not in itself a finding about the gene and the disease.
tumor (continued). "Real-time PCR analysis showed that at the tumor tissue level, the expression of E-cadherin was upregulated after the knockout of ST8SIA6-AS1, whereas the expression of vimentin decreased in nude mouse tumor tissues." (PMID 35783150, 2022). "Since expressions of c-MYC, cyclin D1, and vimentin were reduced after TUBB4A KO, we analyzed the mRNA expression of β-catenin-targeted genes c-Myc, Ccnd1, and Vim in microdissected tumor cells." (PMID 35589707, 2022). "Our data further showed that miR-1278 mimic inhibited EMT process via markedly promoting the expression of vimentin while downregulating e-cadherin in CRC cells and tumor samples from xenograft model." (PMID 33791222, 2021). "For these analyses, we excluded tumor-associated markers expressed in more than 90% (CK7, CK19, CKLMW, CKHMW, and MUC1) or less than 10% (vimentin and MUC2) of the tumor samples." (PMID 33494186, 2021). "As reported in a recent paper concerning tumor buds, single cells and small cell clusters (<5 cells) at the tumor invasion front of CRC show Vimentin/pan-Cytokeratin positive staining and are suggested to be in an intermediate state, with partial EMT." (PMID 35008299, 2021). "The detection and analysis of CTC markers (EpCAM and CK8, 18, CD45 Vimentin,Twist and 19) and CSCs markers (NANOG) are of great value in the evaluation of tumor progression." (PMID 34123777, 2021). "Immunohistochemistry of the tumor showed AE1/AE3 (+), Ki-67 (2% +),α1-ACT (+), AB-PAS (+), CK7 (+), Calponin (±), Vimentin (+), CK19 (+)." (PMID 34663287, 2021). "CDH1 (E-cadherin) expressions always served as tumor suppressors during carcinoma EMT, while the hallmarks of EMT are the upregulation of CDH2 (N-cadherin) and vimentin." (PMID 34631545, 2021). "With increasing of the size of primary tumor, the number of CTCs in the following three populations increased: CD45–EpCAM+CK7–Snail–N-cadherin–Vimentin–, CD45–EpCAM+CK7–Snail–N-cadherin–Vimentin+, and CD45–EpCAM–CK7+Snail–N-cadherin–Vimentin–." (PMID 33801519, 2021). "With advanced tumour grade, the nuclear distribution of PKD3 as well as the levels of PKD3 and Vimentin gradually increased." (PMID 33692335, 2021). "Consistent with the finding that LINC01303 silencing inhibited tumor metastasis in vivo, E-cadherin expression was upregulated in the sh-LINC01303 group, whereas vimentin was downregulated." (PMID 34912458, 2021). "EMT-related molecules including Twist, Slug and Vimentin and MMP-2 play a crucial role in tumor metastasis and invasion." (PMID 33430870, 2021). "Intriguingly, remarkable suppression of Integrin α6, integrin ’β4, metastatic markers—vimentin and MMP-9, and enhanced cleavage of caspase-3 was observed in ATQ-treated tumor lysate." (PMID 34071408, 2021). "More importantly, MSJZD augmented the E-cadherin level and weakened the Vimentin, Snail, TGF-β1, p-AKT, and p-GSK3β levels in A549 tumor-bearing nude mice, which was consistent with in vitro experiments." (PMID 35111070, 2021). "Recent studies had shown that the important markers of EMT, namely vimentin, E-cadherin, FSP1 and EPCAM, that can effectively help us find tumor cells undergoing the EMT process." (PMID 33535187, 2021). "The upregulated MET promotes the downregulation of the epithelial markers of pancreatic cancer cells (FOXA1 and CDH1) and the upregulation of vimentin expression, which eventually promotes the EMT process and increases tumor cell migration." (PMID 33390809, 2021). "Using a standard protocol for monolayer tumor cell growth on tissue-culture-treated plastic in serum-containing medium, primary cell cultures were established and stained for tumor (CK18, vimentin) and fibroblast (PDGFRα/β) cell markers." (PMID 34884982, 2021).
tumor (continued). "MACC1 upregulation resulted in decreased epithelial markers such as E­cadherin and increased mesenchymal markers such as vimentin in certain cancers, thus promoting EMT, tumor invasion and metastasis." (PMID 33854976, 2021). "Collectively, vimentin expression is preeminently characterized in the EMT process, including tumor cell migration and invasion." (PMID 33919917, 2021). "Because the process of EMT leads to organ fibrosis, we compared the expression of mesenchymal markers such as vimentin, α-smooth muscle actin (α-SMA), Snail, and N-cadherin between the MCTS models and tumor spheroids." (PMID 34035369, 2021). "EPHA2 modulates tumor invasion and metastasis by negatively regulating CDH1 (E-cadherin), while also having a positive correlation with vimentin and β-catenin expression." (PMID 34455105, 2021). "Tumor cells with EMT signatures, as evidenced by reduction of the cell adhesion molecule E‐cadherin and overexpression of the mesenchymal molecule Vimentin, display an increased capability of metastasis." (PMID 33934562, 2021). "Increased ectopic expression of miR-22 increased E-cadherin expression, but decreased that of N-cadherin, vimentin, Snail, Slug, and GSK-3β phosphorylation, therefore suppressing EMT in BLCA acting as a tumor suppressor." (PMID 33672684, 2021). "The IHC analyses of tumor tissues similarly revealed that CRSP8 knockdown suppressed the expression of β-catenin, Vimentin, and Ki67, but IKKα knockdown reversed such inhibition." (PMID 33162555, 2021). "Because EMT contributes to increased tumour cell migration and invasion, we assessed the expression of EMT‐related proteins (e.g. E‐cadherin, N‐cadherin, Vimentin and Snail) in these cell sublines." (PMID 34655278, 2021). "Immunohistochemical (IHC) and western blot (WB) assay were used to detect the expression level of E-cadherin, N-cadherin, vimentin, and TWIST1 to evaluate the effect of QFG on tumor cell EMT progression." (PMID 34887935, 2021). "Meanwhile, YAP, IGF-1R, and mesenchymal markers (VIMENTIN and SNAIL1) were consistently observed at the tumor margin." (PMID 34359714, 2021). "EMT is marked by the upregulation of N-cadherin, Vimentin, and ASMA, and downregulation of E-cadherin, which plays a critical role in the process of tumor metastasis." (PMID 34631521, 2021). "Using immunohistochemistry on isolated nude mouse tumor tissues, the results confirmed that ADNP knockdown significantly down-regulated the expression of ADNP, N-Cadherin, and Vimentin after cisplatin intervention, while E-Cadherin expression was the opposite." (PMID 34335928, 2021). "In our study, IPT-like FDCS tumor cells expressed CD21 and CD35, while partly expressing CD68, smooth muscle actin, vimentin, and clusterin." (PMID 33731032, 2021). "The nuclear localization of Snail1 facilitates the expression of mesenchymal markers, such as vimentin and fibronectin, completes the EMT and increases migration, invasion, and metastasis of tumor cells 62-64." (PMID 34149910, 2021). "Correlation between expression of vimentin, a canonical marker of EMT, and malignancy has been broadly studied; however, how vimentin regulates tumor metastasis and survival remains under investigation." (PMID 33963314, 2021). "Xenograft tumor of HCT 116 showed an increased expression of neuronal genes MAP2 and SYN1, neural stemness genes CDH2, MSI1, NCAM1, SOX2/9, VIM and ZEB2, and genes for mesodermal and endodermal tissues (ACP5, AFP, DESMIN, HNF4A and KRT8)." (PMID 33468253, 2021).
tumor (continued). "Double staining was performed using two different antibodies, anti-SMP30 (red) and anti-vimentin (green), for myoepithelial cell markers to visualize the localization of SMP30 expression in tumor tissues." (PMID 33652881, 2021). "The staining intensity of vimentin and AQP4 was also significantly increased in the tumor mass compared to the contralateral hemisphere (p = 0.019 and p = 0.014, respectively)." (PMID 34441246, 2021). "Vimentin is a well‐known biomarker of EMT, which is a fetal developmental process that drives metastasis of tumor cells." (PMID 34605151, 2021). "Then immunofluorescence assays for E-cadherin, vimentin, and p-AKT were performed using serial sections of mouse tumor tissues." (PMID 33968740, 2021). "αEGFR-E-P125A reduced the levels of SER39-phosphorylated vimentin in TNBC cells cultured in matrigel and in tumor deposits in vivo." (PMID 34831127, 2021). "Immunohistochemical examination showed that the tumor cells were positive for both epithelial (cytokeratin AE1/AE3) and mesenchymal cell markers (vimentin)." (PMID 33903966, 2021). "The tumor growth was suppressed after depletion of HCG11, followed by suppressing Ki67, PCNA and Vimentin expression, increasing TUNEL-positive cells and E-cadherin expression." (PMID 34230221, 2021). "The immunohistochemistry of the tumor showed AE1/AE3 (+), Ki-67 (2% +), CK7 (+), Vimentin (+), CK19 (+), α1-ACT (+), AB-PAS (+), S-100 (−), TTF-1 (−)." (PMID 34663287, 2021). "E-cadherin and vimentin are both EMT related proteins, and MMP-2 plays an important role in tumor invasion and metastasis 16,17." (PMID 33613773, 2021). "Compared to controls, tumor displaying lower SNAI1, PECAM1 and VIM and higher TP63, KRT14, KRT5 and PTPRC (CD45) RNAs (PyMT-VE-CadhSnail1KO tumor signature) presented a longer overall survival, strengthen our mice results." (PMID 34335957, 2021). "High levels of vimentin were observed in PBS- or cetuximab-treated tumor sections, but lower levels of vimentin were seen in αEGFR-E-P125A-treated tumor sections." (PMID 34831127, 2021). "Vimentin expression correlated markedly with TNM stage (P = 0.003), tumour differentiation (P = 0.001), tumour size (P = 0.024), and microvascular invasion (P = 0.013)." (PMID 33757532, 2021). "They showed a strong expression of the mesenchymal marker vimentin and N-cadherin, promoting cell migration and metastasis as well as the HNSCC tumor stem cell marker CD44 and overexpression of the oncogenic transcription factor Snai1." (PMID 34884892, 2021). "KRT+ or PSA+ tumour cells were often found on the periphery of CTC clusters, surrounding hybrid-like or mesenchymal-like cells (VIM+ or SERPINE1+)." (PMID 34206049, 2021). "To further unveil potential modulative impact of IGHG1 on tumor cell EMT (epithelial-mesenchymal transition), we utilized western blot and qRT-PCR method to detect several EMT markers (N-cadherin, Vimentin, E-cadherin)." (PMID 34315496, 2021). "Compared with the primary tumor, in the metastasis group, the mesenchymal markers (CDH2, VIM, TWIST1, SNAI1, ZEB1) and ferroptosis drivers increased, and the epithelial marker CDH1 and ferroptosis suppressor decreased." (PMID 35127731, 2021). "In tumor cells of the TE11* group, VIM expression was observed only in mice treated with 5‐FU, whereas it was absent in mice treated with either PBS or 5‐FU in the TE11‐ICN3 group." (PMID 34042293, 2021). "Immunochemically, the tumor cells were positive for CD31, ERG, Fli1, D2–40 and vimentin in a diffused manner." (PMID 33509230, 2021). "Tumor migration and invasion are highly correlated with angiogenesis and EMT process, so Vimentin, E-cadherin, and CD34 were used to evaluate the ability of tumor invasion and migration by IHC." (PMID 33937074, 2021). "Immunohistochemistry showed that the tumor was positive for CK19, S-100, vimentin, mammagloblin, GCDFP15, and MUC4." (PMID 34941172, 2021).
tumor (continued). "In contrast, EM046 cells, isolated from a stage IB undifferentiated tumor, displayed both MMP2 and α-smooth muscle actin expression, as well as vimentin on both protein and mRNA level." (PMID 34936030, 2021). "We validated the expression of ZFAS1, identifying it as a major regulator of tumor progression in CRC, through the critical miR-200/ZEB1/E-cadherin, vimentin signaling cascade." (PMID 33771981, 2021). "Therefore, vimentin may be a potential target for capturing CTCs in patients with tumor." (PMID 34168982, 2021). "Some tumor cells were positive for CD68, smooth muscle actin, vimentin and epidermal growth factor receptor." (PMID 33731032, 2021). "HIF-1α/NRP1 signaling can subsequently result in activation of MMP2, Vimentin, and VE-cadherin and thus promote EMT and VM, which ultimately contribute to tumor progression in LUAD." (PMID 33850110, 2021). "Here, we found that knockdown of FOXD1 significantly promoted E-cadherin expression and reduced N-cadherin and vimentin expression, which implies an inhibited EMT status in the tumor cells." (PMID 34348789, 2021). "Immunohistochemistry showed that the tumor was positive for cytokeratin 19 (CK19), S-100, vimentin, mammagloblin, gross cystic disease fluid protein 15 (GCDFP15), and GATA3." (PMID 34941172, 2021). "As compared with the control group, the tumor volume and weight of mice in the WDR43 knockdown group was reduced, while the tumor volume and weight of mice with both WDR43 knockdown and VIM overexpression were significantly recovered." (PMID 34372874, 2021). "Immunohistochemically, the tumor cells were diffusely positive for vimentin and focally positive for CD34 and alpha-SMA; lipoblasts within the tumor were focally positive for S-100." (PMID 34797454, 2021). "Tumours also demonstrated increased positivity for the CAF marker, vimentin (P < .01) in Rux as a single agent and in combination treatment over vehicle." (PMID 33274592, 2021). "Western blot and RT-PCR analysis of tumor tissues also showed that CRSP8 knockdown decreased the expression of β-catenin and Vimentin, but increased the expression of NIS and Tg, and such expression changes were rescued by IKKα knockdown." (PMID 33162555, 2021). "To identify the most potent tumor cell-targeted cytotoxic drugs, we compared the GR-corrected IC50 estimates of the drugs between the KRT19+ and VIM+ cells." (PMID 34604070, 2021). "Immunohistochemically, the tumor was positive for immunohistochemical markers for CK AE1/AE3, Vimentin, S100, Brachyury, epithelial membrane antigen (EMA) and epidermal growth factor receptor (EGFR)." (PMID 34717660, 2021). "In our study, ALX1 overexpression promoted tumor progression in EC at least partly through upregulation of MMP2, MMP9, VEGF and vimentin." (PMID 34104082, 2021). "As vimentin expression is an early event in normal glial differentiation, while GFAP only appears in later stages, this indicates that the majority of tumor cells in these GB tumors were neoplastic astrocytes in a dedifferentiated state." (PMID 34441246, 2021). "In view of the regulation of E-cad, MMP-9, MMP-2, and vimentin, the results showed that TPL/NPs effectively suppressed tumor metastatic effects in vivo." (PMID 34162396, 2021). "IHC images showed positive expression of E-cadherin in tumor sections was significantly higher in mice with LBX2-AS1 knockdown, and those of Ki-67, N-cadherin and Vimentin were lower than controls." (PMID 34729101, 2021). "Next, the qRT-PCR results illuminated that MSJZD and cisplatin augmented the E-cadherin level and weakened the Vimentin, Snail, TGF-β1 levels in A549 tumor-bearing nude mice." (PMID 35111070, 2021). "In our cases, immunostaining revealed that the tumor was positive for CK19, S-100, vimentin, mammaglobin, GCDFP15, GATA3, and MUC4." (PMID 34941172, 2021).
tumor (continued). "With increasing of the tumor grade from T1 to T2, among the 24 discussed CTC populations, the number of CTCs with CD45–EpCAM+CK7+Snail–N-cadherin+Vimentin+ phenotype decreased (0.00–0.83) cell per ml and 0.83 (0.83–2.22) cells per ml, respectively, p = 0.023)." (PMID 33801519, 2021). "EMT-related molecules (Twist, Slug, Vimentin and MMP-2) even play an important role in tumor metastasis and invasion." (PMID 33430870, 2021). "The induction by USP22 promotes tumour invasion and epithelial-to-mesenchymal transition (EMT), leading to downregulation of E-cadherin and upregulation of N-cadherin, vimentin and matrix metalloproteinases (MMP)." (PMID 34226501, 2021). "Immunochemically, the tumor cells were positive for CD31, ERG, Fli1, D2–40 and vimentin in a strong and diffused manner." (PMID 33509230, 2021). "The alteration of EMT was evaluated by targeting E-cadherin, vimentin, and CD133 in PCFE alone and in combination with dacarbazine-treated tumor tissues by western blot analysis." (PMID 34007300, 2021). "Western blot results revealed that the levels of p‐STAT3 (Tyr705), vimentin, MMP‐13, and MMP‐3 decreased in the tumor tissues grown from HeLa cells in the RES pretreatment and treatment groups, compared with those in the respective control groups." (PMID 33040485, 2020). "E-cadherin, N-cadherin, β-catenin, Vimentin, Wnt-5β, Twist, Snail, and EIF4E-BP1 protein levels were greater in SRA-overexpressing tumor than those in control tumors." (PMID 31892849, 2020). "ADSC exosome-treated tumor cells expressed higher levels of COLGALT2 and vimentin than control cells." (PMID 32523950, 2020). "DSTYK expression is positively proportional to the expression of TGF-β, mesenchymal markers vimentin (VIM) and N-cadherin (CDH2) in tumor tissues from human CRC patients, whereas it is inversely correlated to epithelial marker E-cadherin (CDH1) expression." (PMID 32982725, 2020). "Tumor migration is always accompanied by EMT, which exhibits decreased E-cadherin expression along with increased N-cadherin and Vimentin expressions." (PMID 32776110, 2020). "When EMT occurs in tumor cells, obvious changes in the expression level of EMT markers can be detected: E-cadherin is downregulated, while vimentin and N-cadherin are upregulated." (PMID 32294699, 2020). "The correlations of ZNF750 with SNAI1, VIM, CDH2 and CDH1 were verified with our RNA sequencing data of 155 paired of ESCC and matched non-tumor tissues." (PMID 32042337, 2020). "Over-expression of PBXIP1 (HPIP) has been shown to inhibit apoptosis by up-regulating BCL2, to promote tumor cell proliferation via activation of ER, and to mediate EMT by regulating mesenchymal genes such as N-cadherin and Vimentin." (PMID 33194730, 2020). "In addition, we were able to show that POSTN expression was predominantly localised in tumour stroma cells, i.e., in CAFs, as evidenced by the positive IHC staining and a very similar pattern in the serial sections for POSTN and CAF-associated markers, i.e., α-SMA, D2-40, and vimentin." (PMID 32987711, 2020). "The overexpression of GRP75 in hepatocellular carcinoma cells was correlated with vimentin expression and promoted EMT, forming the metastatic tumor cell phenotype." (PMID 32268506, 2020). "Interestingly, the percentage of cases reacting with the N-terminal region of vimentin was even higher than the percentage of cases reacting with HEp-2 cells, indicating the existence of different conformational epitopes that can be recognized by the tumor immunoglobulins." (PMID 32481736, 2020). "Total RNA was extracted from subcutaneous tumours and metastatic nodules, and the mRNA levels of EMT-related markers (E-cadherin, Vimentin, Twist, Slug and N-cadherin) were evaluated." (PMID 32231199, 2020). "The connective tissues expressed positive staining of vimentin compared to epithelial SCC cells in the initial subcutaneous tumor and orthotopic tumor grafts." (PMID 32131500, 2020).